TXN (thioredoxin)
Diseases named in the same sentence as TXN in open-access papers (continued):
Sharing a sentence is not in itself a finding about the gene and the disease.
tumor (continued). "Thioredoxin is upregulated in a wide variety of tumours such as mesothelioma, leukaemia, lung, hepatocellular and renal cancer." (PMID 15655539, 2005). "From current results, we conclude that AW464, a novel thioredoxin inhibitor, is an effective drug in vitro against tumour cells." (PMID 15655539, 2005). "Thus, the thioredoxin and glutathione antioxidant systems play unique roles in tumor initiation and progression." (PMID 40334547, 2025). "For example, neutralization of tumor-derived Gal-1 with a thioredoxin-mouse Gal-1 therapeutic vaccine boosted the infiltration and cytotoxic activity of Tc cells against the tumor, promoted the normalization of the tumor vasculature, and decreased tumor burden." (PMID 40178639, 2025). "Altogether, this indicates that agents that induce ferroptosis through TrxR inhibition might affect multiple pathways or proteins in addition to the thioredoxin pathway, and these could contribute to anti-tumor effects and compatibility with chemotherapy." (PMID 40957885, 2025). "Furthermore, in both monotherapy and combination groups, RARA knockdown resulted in reduced tumor volume and weight, an effect that was reversed by overexpression of TXN and PPM1F, which was consistent with vitro experiments." (PMID 38902322, 2024). "Therefore, TXNIP upregulation attenuates the activity of TXN, leading to decreased proliferation and cell cycle progression in tumor cells." (PMID 37037466, 2023). "In addition to its regulation of redox balance, TXN can interact with different proteins to regulate tumor development through redox-dependent signaling pathways." (PMID 36776308, 2023). "Furthermore, our data suggest that the presence of neutrophils in the TME are necessary for thioredoxin to elicit a tumor suppressing effect." (PMID 35250998, 2022). "Therefore, thioredoxin impairs induction of TNFα inflammatory cytokine production during tumor initiation." (PMID 35250998, 2022). "Thioredoxin can also alter inflammatory signaling in the tumor microenvironment." (PMID 35250998, 2022). "In tumor progression, thioredoxin is typically found to be tumor-promoting." (PMID 35250998, 2022). "Taken together, our findings suggest that thioredoxin inhibits neutrophil recruitment and retention around transformed cells in vivo, possibly by regulating the redox status and cytokine production in the tumor microenvironment." (PMID 35250998, 2022). "The TXN system is also known to exhibit tumor suppressive abilities." (PMID 33477494, 2021). "PRDX1 cooperates with thioredoxin in inhibiting ROS-induced tumor cell apoptosis and promoting tumor cell survival by involving different types of kinases and enzymes, such as apoptosis signal-regulating kinase 1, p66Shc, and glutathione S-transferase pi (GSTpi)/c-Jun NH2-terminal kinase (JNK)." (PMID 33747258, 2021). "Secondly, the amount of leptin in the gastrocnemius correlated positively with the amount of soluble PECAM and MMP2 in the same tissue as well as with different actors of the tumour oxidative status (total glutathione, glutathione-S-transferase, glutathione reductase, thioredoxin and COX-2)." (PMID 32472095, 2020). "The management of mitochondrial ROS levels is a key feature of acute myeloid leukemia, where the protein kinase-ε activation controls the content of mROS by impacting on some ROS-buffering enzymes, such as thioredoxin and glutathione synthetase, thereby promoting the tumor progression in vivo." (PMID 32185131, 2020). "However, it needs to be stressed that ROS severely impair NK-cell activity and survival, as IL-15-primed NK-cells upregulate thioredoxin activity to protect themselves from cytotoxic ROS in the tumor microenvironment (TME)." (PMID 33265951, 2020). "Many compounds have been studied for their activity to modulate thioredoxin system in tumor cells." (PMID 27911871, 2017).
tumor (continued). "In this study, we asked whether AF may in addition radiosensitize tumor cells by targeting thioredoxin reductase (TrxR), a critical enzyme in the antioxidant defense system operating through the reductive protein thioredoxin." (PMID 28415723, 2017). "Furthermore, inhibition of GSH and thioredoxin antioxidant pathways or selective activation of the Akt pro-oxidant pathways led to synergistic tumor regression confirming the remarkable potency of excessive ROS when harnessed for tumor eradication." (PMID 27458571, 2016). "In order to effectively eliminate ROS and to cope with the damaging effects from ROS mediated stress, tumor cells have developed antioxidant defense mechanisms which include non-enzymatic radical scavengers and cellular antioxidant systems, of which the thioredoxin (Trx) system is a key player." (PMID 27588488, 2016). "We hypothesize that TXN may be involved in the TGF-β-mediated EMT-induced tumor mobility and invasion in SACC." (PMID 26325518, 2015). "However, little is known about the role of TXN in tumor mobility and invasion during the process of TGF-β-induced EMT." (PMID 26325518, 2015). "The use of long-circulating pegylated liposomes with a prodrug requiring thiolytic and reductive activation to generate an alkylating species was intended to target the drug in a controlled release mode to tumor tissue, which often overexpresses thioredoxin signaling 12,21." (PMID 26172205, 2015). "The relationship of thioredoxin with tumor size, Child-Pugh class and tumor stage were evaluated." (PMID 25871387, 2015). "Inhibiting either thioredoxin or DJ-1 alone may allow the other antioxidant to activate downstream signalling cascades leading to tumour cell survival and proliferation." (PMID 25593990, 2014). "This review focuses on the role of thioredoxin in the various states of tumor oxygenation." (PMID 24281068, 2010). "The inverse association of TXNRD1 and TXNIP with MFI found in this study supports the hypothesis that the maintenance of an active thioredoxin system is advantageous to the tumor cells because it limits oxidative damage and enables them to survive." (PMID 20584310, 2010). "Therefore, tumor cells must require strong ROS-scavenging systems (such as HO-1, superoxide dismutase, catalase, peroxiredoxin, thioredoxin, glutaredoxin, and glutathione peroxidase) to eliminate ROS, in which the HO-1 antioxidant system plays an important role." (PMID 37765244, 2023). "These also indicated that inhibition of TXN could significantly affect tumour cell survival." (PMID 35597868, 2022). "In addition, targeting the thioredoxin pathway may further synergise with GSH-targeting drugs in lowering the reductive capacity of tumour cells, in order to sensitise them to oxaliplatin and increase local treatment efficacy." (PMID 35194192, 2022). "Therefore, thioredoxin may have a distinct role during tumor initiation as compared to more developed tumor models used in other studies." (PMID 35250998, 2022). "However, it is not known whether Bcl-2 or other apoptotic regulators can influence the levels of thioredoxin or whether such modulation may contribute to resistance in human tumor cells." (PMID 19061505, 2008). "TXNIP, as well as TXN and TXNRD1 have been demonstrated in several studies to regulate tumor immunity, especially T-cell function and differentiation." (PMID 39744566, 2025). "Using TCGA datasets, we then explore the mRNA levels of TXN, TXNRD1, and TXNIP in tumor and adjacent normal tissues and found similar results." (PMID 39744566, 2025). "The high expression of TXN and TXNRD1, as well as the low expression of TXNIP group exhibited lower levels of tumor immune infiltration." (PMID 39744566, 2025). "We evaluated the stromal and immune cells in tumor tissues using the ESTIMATE method, and found that stromal and immune scores were lower in the high TXN, high TXNRD1, and low TXNIP groups in most tumor species." (PMID 39744566, 2025).
tumor (continued). "Using the CPTAC database, we verified that TXN, TXNRD1 and TXNIP proteins were also aberrantly expressed in the tumor." (PMID 39744566, 2025). "This study aimed to determine of TXNIP and TXN expression and their cellular localisation in ESRD/ACRD kidneys, tumour precursor lesions and tumours by immunohistochemistry." (PMID 39020292, 2024). "Tumor xenografts were generated with NC, RARA-SH1, NC + TXN-OE + PPM1F-OE, and RARA-SH1 + TXN-OE + PPM1F-OE cell lines." (PMID 38902322, 2024). "Strong TXNIP expression was seen in epithelial cells, myo-fibroblasts and endothelial cells and weak TXN expression in ESRD/ACRD kidneys and tumours." (PMID 39020292, 2024). "PKP2, TXN, and ZNF292 are also abnormally expressed in tumors and induce radioresistance of tumor cells." (PMID 37101691, 2023). "PRDX6, MAGOHB, NUCKS1, DCAF13, and TXN displayed opposite trends on their potential facilitation of CTL function as well as correlations with immune checkpoints and TILs (tumor-infiltrating lymphocytes) compared to ITGAL, ITGAX, and TMEM119 in NSCLC." (PMID 37835514, 2023). "have demonstrated that antioxidant protein thioredoxin (TRX) enhances Treg cell infiltration in melanoma, which in turn decreased anti-tumor immune reactions." (PMID 36569832, 2022). "The increased expression of cytotoxic effector molecules GZMA, GZMB, GZMH, GZMM, GNLY, NKG7, and PRF178 but also of the thioredoxin function inhibitor TXNIP79, demonstrates a potent effector capacity to eliminate malignant cells and suppress tumor growth." (PMID 33602930, 2021). "To better understand the increased ROS-mediated damages in tumor tissues, we assessed the protein expression of three major antioxidant proteins, super oxide dismutase (SOD), catalase, and thioredoxin (TXN)." (PMID 33799792, 2021). "It revealed that all these five targets (GSN, ADAMTSL4, CALR, PPIA and TXN) can be secreted by the NPC 6-10B and 5-8F cells, which provided an important basis for our following studies to identify the serum tumor biomarkers of NPC." (PMID 28107202, 2017). "Over-expression of [GRP78 and HSP27] prevented: AR-12 –induced activation of ER stress signaling and maintained mTOR activity; AR-12 –mediated down-regulation of thioredoxin, MCL-1 and c-FLIP-s; and preserved tumor cell viability." (PMID 26887051, 2016). "All seven glucose metabolism-related proteins were downregulated in SBP1 induced-tumor tissue, including GAA, GAPDH, ALDH2, Thioredoxin, ENO3, UGDH and Lumican." (PMID 25974208, 2015). "The thioredoxin system including thioredoxin, thioredoxin reductase and nicotinamide adenine dinucleotide phosphate (NADPH) is involved in aspects of tumor physiology such as proliferation, apoptosis, and metastasis." (PMID 26325518, 2015). "Thioredoxin (TXN) is overexpressed in BC, and it is related to tumor grade, being a crucial element in redox homeostasis." (PMID 25416100, 2014). "Tumor cells can respond to these conditions by upregulating several cellular mechanisms to counteract the resulting redox imbalance, the most important of which involve the glutathione (GSH) and thioredoxin (TXN) systems." (PMID 41346571, 2025). "Therefore, genetic depletion of TXN and TXNDR1 with siRNA oligonucleotides disrupts the redox balance mediated by the Trx system in tumor cells, thereby contributing to the inhibition of cell proliferation." (PMID 39744566, 2025). "The existence of extracellular AGR2 can transform non tumor organs into tumor organs and enhance their growth by about 10 times, which is independent of its thioredoxin folding and endoplasmic reticulum retention motif." (PMID 37197416, 2023). "The expression of SBP1, TXN, TSH-R, TG and NIS in tumor tissues was analyzed by Western blot." (PMID 37684566, 2023). "Third, we focused mainly on how TXN inhibitors affected radiotherapy in tumour cells and did not consider the crucial role of chemotherapy in CRC cancer patients." (PMID 35597868, 2022).
tumor (continued). "The TXN components, for example TXN and TXNRD1, are reported to promote tumor growth." (PMID 33477494, 2021). "Histopathological assessment of SCC lesions revealed that 12 patients (80%) had grade I, and 3 patients (20%) had grade II of tumor; however, there was not any remarkable correlation between tumor grade and salivary thioredoxin levels (p = 0.219)." (PMID 33289312, 2020). "In addition, suppressing the TXN-based antioxidant system by targeting TXN using PX-12 and targeting TXNRD using auranofin or motexafin gadolinium have also been proposed to sensitise tumours to radiotherapy." (PMID 33276631, 2020). "The present data show for the first time that the ADAMTSL4 and TXN may be novel and potential biomarkers for predicting the NPC metastasis.Furthermore, the serum ADAMTSL4 could be a potential serum tumor biomarker for prognosis of NPC." (PMID 28107202, 2017). "The redox potential of MIEN1 was found between that of thioredoxin and protein disulfide isomerase (−175 mV), so MIEN1 may catalyze the reduction and/or isomerization of disulfide bonds for tumor-related proteins." (PMID 23284973, 2012). "Increased levels of antioxidant enzymes (SOD, catalase, glutathione peroxidase) and non-enzymatic antioxidants (GSH, vitamin C, thioredoxin) are significant in several clinical tumor burdens." (PMID 16759382, 2006). "Each clinically detected tumour in ESRD/ACRD kidney is accompanied by multiplex pre-neoplastic lesions showing similar histological pattern, which may explain the field effect of imbalance of TXNIP/TXN redox system and elevated ROS." (PMID 39020292, 2024). "This broader activity spectrum can be explained by the fact that the therapeutic dosage of SAHA for tumor cells lies significantly below that for non-transformed cells, so that the thioredoxin-protection of normal cells is only breached in higher concentrations." (PMID 25228443, 2014). "The activities of thioredoxin (Trx1) and thioredoxin reductase (TrxR1) were significantly elevated, whereas treatment with either curcumin, an irreversible inhibitor of TrxR1, or adiponectin largely attenuated their activities and resulted in the re-activation of PTEN in these tumor cells." (PMID 19319191, 2009).
infection (61 papers, 2008 to 2026). The state of being infected such as from the introduction of a foreign agent such as serum, vaccine, antigenic substance or organism. "In summary, for the first time, we revealed the biological roles and the underlying regulatory mechanisms of the putative thioredoxin YjbH in the oxidative stress tolerance and intracellular infection of the foodborne pathogen L. monocytogenes." (PMID 33573432, 2021). "Tight regulation of virulence proteins is essential for a successful infection, and the gene encoding the annotated thioredoxin YjbH was identified in two forward genetic screens as required for virulence factor production." (PMID 32253340, 2020). "Peroxiredoxin 1 and 2 have been identified to maintain molluscan health through catalysing the interaction between thioredoxin and hydrogen peroxide and are also expressed earlier in resistant strains than susceptible ones following infection." (PMID 31521183, 2019). "Four genes (HIM_00696, HIM_03743, HIM_08072, and HIM_08834) encoding thioredoxin (PF00085) acting as antioxidants were activated during infection stage." (PMID 25359922, 2014). "During infection of blast pathogen on resistant and susceptible cultivars, primary response leads to respiratory burst that includes redox state genes like glutathione, glutaredoxin, thioredoxin, redoxin glutathione S-transferases and peroxidase." (PMID 33672641, 2021). "Similarly, here we describe the importance of the extracellular thioredoxin Etrx3 on the intracellular survival of R. equi, an actinobacterial pathogen causing infections that are becoming very difficult to treat due to antibacterial resistance." (PMID 32156317, 2020). "SigH is critical for long-term infection persistence, mainly through activation of thioredoxin (trx) genes, essential for redox homeostasis inside macrophages." (PMID 41450943, 2025). "Thioredoxin has also been reported to intervene in the intracellular infection and virulence of Salmonella typhimurium." (PMID 41040986, 2025). "Accordingly, N. ceranae employs the thioredoxin and glutathione systems to defend against oxidative stress and maintain a balanced redox equilibrium, which is essential for the infection process." (PMID 37210527, 2023). "TR neutralizes hydrogen peroxide produced by macrophages during infection through the tryparedoxin/tryparedoxin peroxidase I (TXN/TXNPx) system." (PMID 35242720, 2022). "Cluster II, including genes downregulated after infection, dominated (57.14%); among this cluster are genes encoding 3 SOD, 1 CAT, 12 peroxidase, 2 glutaredoxin, 1 peroxiredoxin, and 5 thioredoxin." (PMID 35616396, 2022). "During infection, the transcript levels of genes in glutaredoxin and thioredoxin systems were significantly downregulated in the ΔLtap1 mutant." (PMID 34630367, 2021). "Since SARS-CoV-2 contains cysteine-rich spike glycoproteins, an infection mechanism involving Thioredoxin was proposed, where the surface proteins can benefit from an ROS-rich environment." (PMID 34571838, 2021). "The mutant showed severely reduced transcription levels of genes related to glutaredoxin and thioredoxin in L. theobroame under oxidative stress or during infection, indicating an attenuated capacity for reactive oxygen species (ROS) detoxification." (PMID 34630367, 2021). "We found that LtAP1 was a key regulator of oxidative stress response, acting in activating fungal glutaredoxin and thioredoxin systems, and suppressing plant defense responses during infection." (PMID 34630367, 2021). "TrxR, which works in conjunction with thioredoxin, is induced in Paracoccidioides during oxidative stress and infection assays." (PMID 30804901, 2019). "The TrxR, which works in conjunction with thioredoxin, is induced in Paracoccidioides during oxidative stress and infection assays." (PMID 30804901, 2019). "To functionally assess fungal thioredoxin activity, we quantified thiol levels in yeast cells of P. brasiliensis at 6 h post-infection of mouse lung." (PMID 28704618, 2017).